APC (APC regulator of Wnt signaling pathway)
Diseases named in the same sentence as APC in open-access papers (continued):
Sharing a sentence is not in itself a finding about the gene and the disease.
rectal cancer (continued). "To uncover the metabolic pathways aberrantly regulated in APC/KRAS-mutant CRC, we utilized the RNA-seq datasets from the Cancer Genome Atlas (TCGA) colon and rectal cancer (COAD-READ) cohorts." (PMID 35803966, 2022). "Interestingly, TRPM7 expression was positively correlated with APC and KRAS gene expression in rectal cancer." (PMID 36363540, 2022).
Gardner syndrome (35 papers, 2012 to 2025). Gardner syndrome is a severe form of familial adenomatous polyposis characterized by multiple adenomas in the colon and rectum associated with prominent extracolonic features including osteomas and multiple skin and soft tissue tumors. "Gardner syndrome is a rare genetic disorder caused by mutations in the APC gene, leading to the formation of osteomas, epidermoid cysts, fibromas, and BCCs." (PMID 40357462, 2025). "A genetic predisposition should also be considered, particularly Gardner syndrome, in which APC gene mutations are associated with multiple osteomas, intestinal polyposis, and soft tissue tumors." (PMID 41523496, 2025). "In most cases this reflects somatic, stabilizing mutations of CTNNB1 (β-catenin; 85–90%), which promote nuclear β-catenin accumulation and transcriptional activation; 10–15% of cases are instead related to germline APC mutations (FAP/Gardner syndrome)." (PMID 41227209, 2025). "Given the possible association between TM and Gardner syndrome, the patient underwent gene sequence and deletion/duplication analyses of the APC gene." (PMID 38172762, 2024). "The majority of patients with classic FAP carry mutations in the N-terminal region, whereas patients with Gardner syndrome harbor mutations localized in the middle region of the APC protein." (PMID 39125758, 2024). "We identified a new mutation in the APC gene that results in supernumerary teeth in association with Gardner syndrome." (PMID 28782241, 2018). "Sequencing analysis revealed that an APC gene mutation in exon 15, namely 4292‐4293‐Del GA, caused Gardner syndrome in this family." (PMID 28782241, 2018). "The APC gene mutation we reported in this manuscript in exon 15, 4292‐4293‐Del GA caused Gardner syndrome in this family is a novel mutation." (PMID 28782241, 2018). "In some studies, the Gardner's Syndrome sub-type of FAP is associated with severely truncated forms of APC." (PMID 27768599, 2016). "WES revealed a novel germline frameshift variant (p.E1554fs) in APC, establishing a diagnosis of Gardner syndrome, along with a somatic nonsense (p.R790*) APC mutation in the tumor." (PMID 27799065, 2016). "Although mutations in the APC gene are associated with Gardner-syndrome-related extra-abdominal desmoid lesions, sporadic lesions are a result of mutations in the β-catenin-coding CTNNB1 gene." (PMID 22966217, 2012). "Gardner's syndrome is also caused by APC mutations, and Turcot syndrome is suspected to be due to APC gene mutation or mismatch repair gene mutations." (PMID 22997602, 2012). "The mutations of APC may cause Gardner syndrome, besides gene mutations of Ror2, Dvl1, Dvl3 and Wnt5a are associated with Robinow syndrome." (PMID 37194731, 2023). "Two mutations in APC, including a somatic nonsense mutation (p.R790*) as well as a novel germline frameshift variant (p.E1554fs), were identified supporting a diagnosis of Gardner syndrome." (PMID 27799065, 2016). "However, given their increased prevalence in those with Gardner syndrome, the roles of adenomatous polyposis coli (APC) gene mutations and β-catenin regulation have been investigated." (PMID 22966217, 2012). "Therefore, loss-of-function of APC found in FAP or Gardner’s syndrome leads to the activation of the β-catenin pathway for regulating gene expression, which may promote odontomas." (PMID 30862786, 2019). "However the bone defects and multiple skin lesions that characterize Gardner's syndrome suggest that alterations in the function of vitamin D pathway genes together with APC mutation may play a role in this deadly disease." (PMID 27768599, 2016). "Gardner’s syndrome is a variant of the Familial Adenomatous Polyposis (FAP), caused by germline mutations in the adenomatous polyposis coli (APC) gene." (PMID 39918719, 2025).
Gardner syndrome (continued). "Young age, male gender, abdominal disease site, family history of bowel cancer, and absence of CTNNB1 tumour mutation are risk factors for Gardner syndrome and should prompt investigation for germline APC mutation or colonoscopy." (PMID 38734790, 2025). "In this study, an APC gene deletion was identified in the Gardner syndrome pedigree." (PMID 28782241, 2018).
colorectal polyps (32 papers, 2008 to 2026). "Familial adenomatous polyposis (FAP) is characterized by colorectal polyposis resulting from a germline pathogenic variant in the adenomatous polyposis coli (APC) gene." (PMID 39776297, 2025). "Ten germline pathogenic variants from 12 FAP pedigrees and whole APC deletion in two patients were identified, for whom 99 colorectal polyps were analyzed for association between germline and somatic mutations." (PMID 41488735, 2025). "In this study, we investigate the role of deep intronic germline APC variants and mosaic APC variants in leukocyte DNA as possible genetic causes of colorectal polyposis in a Dutch cohort of unexplained patients with more than 50 polyps." (PMID 33683519, 2022). "It is characterised by colorectal polyps, due to a mutation in the adenomatous polyposis coli (APC) gene." (PMID 32423157, 2020). "A significant group of patients with multiple colorectal polyps remains genetically unexplained after extensive testing for pathogenic APC and MUTYH variants." (PMID 25604157, 2015). "An additional rare 10 bp deletion in intron 2 of APC (chr5:g.112765678_112765687del) detected in the index (IV:3) was not considered pathogenic as it was also observed in her unaffected sister (IV:1), and no other pathogenic variants were found in genes associated with colorectal polyposis." (PMID 40180948, 2025). "In family 2, a splice donor site mutation in APC exon 12 (c.1621_1626+7del, p.A517_Q542del) leading to exon 12 skipping was identified in a 53-year-old male patient who developed ≥20 colorectal adenomatous polyps and had a family history of colorectal polyposis and CRC." (PMID 39518056, 2024). "Probands with mutations between codon 1250 and 1468 in the APC gene, which predict a severe course of the colorectal polyposis were significantly younger at diagnosis compared with those with mutations outside this region and seem to have more colorectal polyps." (PMID 18433509, 2008). "Using targeted NGS, 379 patients with unexplained colorectal polyposis were tested for APC mosaicism." (PMID 38238650, 2024). "Adenomatous polyposis coli (APC) is a tumor-suppressing protein whose inactivation triggers the formation of colorectal polyps." (PMID 33597597, 2021). "A previous study of patients presenting with CRC or colorectal polyps found APC methylation present in 8/50 (16%) samples." (PMID 33352971, 2020). "APC and MUTYH are both well-known colorectal polyposis causative genes." (PMID 38647838, 2024). "The results of this study indicate that the deep intronic APC variants investigated in this study are not a cause of colorectal polyposis in this Dutch population." (PMID 33683519, 2022). "We did not detect mosaic or intronic APC variants in the screened unexplained colorectal polyposis patients." (PMID 33683519, 2022). "In this study a reanalysis of the entire coding region of APC was performed in a group of 171 patients with ≥10 colorectal polyps, without previously detectable pathogenic APC (or MUTYH) variants." (PMID 25604157, 2015). "For 171 patients with multiple colorectal polyps without previously detectable pathogenic variant, APC was reanalyzed in leukocyte DNA by one uniform technique: high-resolution melting (HRM) analysis." (PMID 25604157, 2015). "In conclusion, rescreening of APC by a uniform sensitive detection method like the described HRM method detects heterozygous and mosaic variants previously missed by different conventional methods in group of genetically unexplained patients with multiple colorectal polyps." (PMID 25604157, 2015). "It was reported that APC and KRAS mutations in colorectal polyps were more frequent among smokers compared to non-smokers." (PMID 29258461, 2017).
endometrial cancer (29 papers, 2012 to 2025). Primary or metastatic malignant neoplasm involving the endometrium (mucous membrane that lines the endometrial cavity). "Nevertheless, APC mutations in endometrial cancer are bi‐allelic, specifically occur in cancers with polymerase proofreading deficiency, and almost never co‐occur with the more frequent CTNNB1 mutations, which also drive Wnt activation." (PMID 40545636, 2025). "Using lineage-tracing experiments, we found that the LysM + EECs give rise to 15% of all EECs in mice, and loss of APC in the LysM + EECs resulted in endometrial hyperplasia, a precursor for endometrial cancer." (PMID 36548952, 2023). "Loss of heterozygosity and promoter hypermethylation of APC is frequently observed in human endometrial cancer, which is the most common gynecological cancer in the USA, but its carcinogenic driver status in the endometrial epithelium has not been confirmed." (PMID 36548952, 2023). "In human endometrial cancer, APC expression can be attenuated by either mutation or promoter methylation." (PMID 36548952, 2023). "An aberrant APC promoter mutation is found in early endometrial carcinoma, which decreases with cancer progression, suggesting that loss of APC function is an early event in endometrial carcinoma." (PMID 35359365, 2022). "Endometrial stromal cells mutated with APC acquire a myofibroblast phenotype and the stromal cells alone are sufficient to induce endometrial cancer in an engineered mouse model." (PMID 22291919, 2012). "APC mutations were detected in both cohorts despite being uncommon in endometrial cancer." (PMID 34572765, 2021). "Mechanistically, endometrial cancer activates the pathway through either CTNNB1 exon 3 mutations, which prevent β-catenin degradation via phosphorylation, or Adenomatous Polyposis Coli protein (APC) inactivation, which disrupts the degradation complex." (PMID 41050070, 2025). "For example, mutations in the tumour suppressor gene APC are very common in colorectal cancer (CRC), but rare in endometrial cancer." (PMID 40545636, 2025). "However, only half of these APC mutations give rise to truncated proteins; therefore, CTNNB1 mutations are likely to be the dominant WNT-activating mutation in endometrial cancer." (PMID 37048063, 2023). "Both APC and CTNNB1 are mutated in approximately 12% and 30% of endometrial cancers, respectively." (PMID 37048063, 2023). "Although these reports indicate that loss of APC and subsequently increased β-catenin can be correlated with endometrial cancer, loss of APC as an actual driver of carcinogenesis has not been shown." (PMID 36548952, 2023). "Whilst APC mutations give rise to truncated proteins, particularly in CRC, CTNNB1-activating mutations give rise to stabilized β-catenin through point mutations in HCC, endometrial cancer, and pancreatic cancer." (PMID 37048063, 2023). "APC is not commonly mutated in endometrial cancers, although hypermethylation of the APC promoter 1A has been observed in approximately 45% of endometrial cancers." (PMID 36548952, 2023). "Additionally, YY1 was shown to silence APC gene expression in endometrial cancer cells by enhancing EZH2-mediated H3K27me3 deposition on the APC promoter." (PMID 33728560, 2021). "In liver and endometrial cancer, CTNNB1 mutations are common while APC mutations are rare." (PMID 32751567, 2020). "In fact, alterations in the Wnt pathway are commonly observed in endometrial cancer at different signalling levels, e.g., ligands, main effector- β-catenin, APC and Axins that affect executive transcription factors followed by deregulation of downstream effector target genes." (PMID 31134156, 2019). "ARNT2 (Cluster 5), BRAF (Cluster 5), and PAK7 (Cluster 5) were mapped to “Renal cell carcinoma;” APC (Cluster 5), BRAF (Cluster 5), and GSK3B (Cluster 2) were mapped to “Endometrial cancer;” and APC (Cluster 5) and GSK3B (Cluster 2) were mapped to “Basal cell carcinoma” in our results." (PMID 28445522, 2017).
endometrial cancer (continued). "The subgroup of high Ad2Sc had a larger OR than that of low Ad2Sc, indicating that methylation of APC might have occurred or functioned at the early stage of tumorigenesis, which had been found for endometrial cancer." (PMID 24661338, 2014). "Altered Wnt/β‐catenin signaling, as a result of gene alterations such as those found in APC or in CTNNB1 (β‐catenin), has been reported to drive tumorigenesis in numerous tumors including endometrial cancer." (PMID 34318590, 2022). "Reduced expression of genes such as APC, CHFR, Sprouty 2, RASSF1A, GPR54, CDH1, and RSK4 through a similar mechanism of hypermethylation has also been found in endometrial cancer." (PMID 22548175, 2012). "For example, in our recent study, we showed that conditional deletion of Adenomatous Polyposis Coli (APC) in endometrial stromal cells results in their conversion to a myofibroblast phenotype, which was sufficient to initiate endometrial hyperplasia that could lead to endometrial cancer in mice." (PMID 22916036, 2012). "Hypermethylation of the APC promoter is not found in the normal endometrium or in endometrial hyperplasia but is detected in atypical hyperplasia and early endometrial cancer." (PMID 22548175, 2012).
glioma (29 papers, 2011 to 2025). A benign or malignant brain and spinal cord tumor that arises from glial cells (astrocytes, oligodendrocytes, ependymal cells). "Meanwhile, the canonical Wnt signaling pathway has been linked to glioma formation, with the aberrant activation of Wnt signaling often attributed to the inactivation of the APC gene, seen in various cancers, including colorectal cancer." (PMID 38473403, 2024). "To investigate the clinicopahtological features associated with a putative miR-4476/APC/β-catenin/c-Jun positive feedback loop in glioma, we performed immunohistochemistry and in situ hybridization in 87 paraffin-embedded glioma tissue samples." (PMID 32327666, 2020). "In our study, we are the first to demonstrate in glioma cells that YTHDF2 binds to m6A -modified APC and GSK3β mRNA, promoting their degradation and thereby activating the Wnt-β-Catenin pathway." (PMID 38637831, 2024). "Brain tissues generally demonstrate the highest expression of APC and, concordantly, low-grade gliomas display the highest expression of APC among all TCGA cancer subtypes." (PMID 39375704, 2024). "For each individual sample, we also assessed the overall level of APC expression (transcripts per million) per sample and divided the TCGA low-grade glioma cohort into quartiles based on APC expression." (PMID 39375704, 2024). "The mechanistic analyses indicated that the adenomatous polyposis coli (APC) was directly targeted by miR-4476 and mediated the oncogenic effects in glioma cells." (PMID 37444408, 2023). "Further mechanistic analyses indicate that the adenomatous polyposis coli (APC), a negative regulator of the Wnt/β-catenin signaling pathway, is a direct target of miR-4476 and mediates the oncogenic effects of miR-4476 in glioma." (PMID 32327666, 2020). "We suspected that nonsignificance was due to small sample size, so we reanalyzed the correlation between OS and APC expression, as well as OS and c-Jun expression, in glioma patients through the GEPIA website and CGGA database." (PMID 32327666, 2020). "In conclusion, our study demonstrates that miR-4476 acts as a tumor enhancer, directly targeting APC to stimulate its own expression and promoting the malignant phenotypes of glioma." (PMID 32327666, 2020). "Together, these results support that miR-4476 promotes glioma progression by directly targeting APC and activating Wnt/β-catenin signaling." (PMID 32327666, 2020). "We found that the OS rates of glioma patients were positively correlated with APC levels but negatively correlated with c-Jun expression." (PMID 32327666, 2020). "Taken together, our results demonstrated the existence of a positive feedback loop involving miR-4476/APC/β-catenin/c-Jun that promotes glioma cell proliferation, migration and invasion." (PMID 32327666, 2020). "Taken together, these data suggest that mir-218-2 modulates the APC/Cubiquitin–proteasome pathway by targeting CDC27 in glioma cells." (PMID 27974673, 2017). "Previous studies showed that p21 is a prime target for ubiquitination in gliomas, and was dependent on the ubiquitin ligase APC/CCdc20 for its proteolytic degradation by the proteasome." (PMID 25121590, 2014). "GFAP-Cre/RictorloxP/loxP mice developed gliomas reminiscent of human oligodendroglioma staining immunopositive for APC and GalC." (PMID 23077666, 2012). "APC protein has been related to certain syndromes, such as Turcot’s syndrome, which involves the development of primary brain tumors like medulloblastomas and gliomas." (PMID 38139220, 2023).